MIF (macrophage migration inhibitory factor)
Diseases named in the same sentence as MIF in open-access papers (continued):
Sharing a sentence is not in itself a finding about the gene and the disease.
tumor (continued). "As expected, there were significantly higher volumes of subcutaneous tumors in the MIF group compared to the other groups, indicating that in vivo, MIF contributes to tumor progression and could be inhibited by blocking CXCR4-AKT pathway activity." (PMID 29113309, 2017). "MIF secreted from tumor cells attracts MSCs to the lungs in CXCR4-dependent manner." (PMID 28798777, 2017). "FACS analysis of TAM isolated from tumor tissues showed a sustained reduction in MIF expression." (PMID 28471401, 2017). "Also, MIF also promotes tumor growth and metastasis, since MIF can mobilize the myeloid-derived suppressor cells (MDSCs) in the tumor microenvironment, thus augmenting immune suppression by the tumors." (PMID 29247872, 2017). "Furthermore, these MIF-positive exosomes, derived from tumor cells, help form a pre-metastatic niche, establishing the tumor at a secondary site, liver." (PMID 28383487, 2017). "Besides, the frequency of MIF-positive tumor-infiltrating lymphocytes in NPC tissue was positively correlated with patients clinical outcomes." (PMID 27788497, 2017). "Our observations suggest tumor therapies may impact functional MIF levels beyond simple elevation by cancer development, and importantly could potentially lead to mitigation of tumoricidal effects." (PMID 26741693, 2016). "Given the robust tumor promoting activities of MIF, our results suggest that an innate host response to genotoxic stress may mitigate the beneficial effects of cancer therapy, and that MIF inhibition may improve therapeutic responses." (PMID 26741693, 2016). "Cytoplasmic MIF was detected in tumor cells of JL-1, H2052 and MSTO tumors." (PMID 26883190, 2016). "Increased MIF expression and reduced DDX6 expression are both known drivers of angiogenesis and strongly associated with VEGF activity, as such they have been implicated in tumor response to hypoxia." (PMID 26980748, 2016). "Thus, we suggest that MIF secretion in solid tumors can be a mitigating factor to tumor control in common cancer therapies." (PMID 26741693, 2016). "In the context of cancer therapy, elevated MIF secretion could promote potent tumor-cell survival, inflammation, and angiogenic complications." (PMID 26741693, 2016). "Thus tumor cell stress by chemotherapy and radiation can induce MIF secretion through an oxidative stress pathway." (PMID 26741693, 2016). "We therefore tested whether MIF secretion in tumor cells could be induced by H2O2 mediated oxidative stress." (PMID 26741693, 2016). "However, MIF cannot be considered a tumor specific marker as it is constitutively expressed and secreted by numerous cell types and significant levels of MIF can be found in the tissue and circulation of healthy subjects." (PMID 27636991, 2016). "By contrast, human MIF and mouse Mif achieved the second highest correlation (r = 0.72) between human and mouse orthologs, suggesting that MIF has complementary roles in the tumor and mouse stroma." (PMID 26980748, 2016). "Given the many modes of MIF action, it is clear that MIF inhibition could have vast implications regarding cancer therapy and tumor recurrence." (PMID 26741693, 2016). "Furthermore, MIF promotes a pro-inflammatory tumor microenvironment (TME) by induction of cytokines and other mediators of inflammation, such as TNF-α, nitric oxide and prostaglandin E2." (PMID 27636991, 2016). "Because CD11b+GR1+ myeloid cells have gained much attention for their role in tumor immunity suppression as well as for their ability to promote angiogenesis, MIF could support tumor growth by recruiting CD11b+GR1+ myeloid cells." (PMID 26347749, 2015).
tumor (continued). "This and studies by others indicate that blockade of VEGF, angiopoietins, and MIF may be effective in tumor regression." (PMID 26530123, 2015). "This revealed that Mock/HHSEC cells with MIF secretion activated tumorigenesis and tumor growth." (PMID 26087187, 2015). "Tumor-derived MIF levels correlated with higher TANs levels and poor survival of these patients." (PMID 26819959, 2015). "A growing body of evidence implicates the role of MIF in tumor growth and metastasis." (PMID 26352431, 2015). "In addition, tumor-originated MIF leads to enhanced accumulation of interleukin-17-producing subsets of tumor-infiltrating lymphocytes by binding to CXCR4, which can affect patient prognosis." (PMID 26347749, 2015). "Interestingly, MIF, which is secreted in response to hypoxia by different tumor cells, was reported to induce CD11b+GR1+ myeloid cell migration via CD74/CXCR4 and CD74/CXCR2 complexes, as well as through p38 and PI3K activation." (PMID 26347749, 2015). "In addition, migration inhibitory factor (MIF), another tumor-derived chemokine for neutrophils, was identified in HNSCC tumors." (PMID 26819959, 2015). "More recent data have additionally identified the role of the host MIF in regulating tumor growth." (PMID 25050663, 2014). "Of note, tumor-activated HSP90 chaperone complex protects MIF from degradation, suggesting that HSP90 inhibitors could serve as anti-MIF therapeutic agents." (PMID 24939415, 2014). "MIF mediates cell proliferation and protects tumor cells from apoptosis." (PMID 24406307, 2014). "Pro-inflammatory mediators such as MIF may be upregulated in stromal cells in an autocrine manner or a paracrine manner during crosstalk between stromal cells and tumor cells." (PMID 24887129, 2014). "MIF, secreted by tumor cells, could then modulate the immune microenvironment and its neovascularization, favoring escape from immune surveillance and tumor cell dissemination." (PMID 24939415, 2014). "In addition, MIF expression positively correlated with cyclin D1 expression in HCC tissues and was closely associated with HCC tumor size." (PMID 25015194, 2014). "Because MIF and D-DT have similar biological functions, we hypothesized that D-DT neutralizing therapeutic strategies may have a similar impact on tumor biology as demonstrated for MIF." (PMID 24406307, 2014). "The results revealed that MIF siRNA significantly suppressed tumor growth in nude mice." (PMID 25015194, 2014). "The present study demonstrates that MIF may be a potential tumor biomarker and therapeutic target because it is overexpressed in human HCC." (PMID 25015194, 2014). "In an in vivo xenograft model, MIF knockdown reduced the tumor growth rate." (PMID 25015194, 2014). "Thus in patients where metastasis had already occurred, those cases with tumours displaying the highest levels of MIF progressed faster." (PMID 25168062, 2014). "Furthermore, neutrophils activated with tumor-derived MIF enhance the migratory properties of HNC cells." (PMID 24586879, 2014). "Indeed, in the GSE19234 cohort, ~70% of patients whose tumours has lower MIF expression remained alive approaching 40 months of clinical follow-up." (PMID 25168062, 2014). "Given their location just underneath the epithelial layer in the gastrointestinal tract, and their role as key regulators of chronic inflammation, tumor growth, and metastasis, one goal of this study was to investigate the potential for MF to produce MIF in the tumor microenvironment." (PMID 24887129, 2014). "The observed persisting chronic changes suggest a possible mechanism behind chronic inflammation and tumor progression, which may make MIF a therapeutic target for gastrointestinal cancers." (PMID 24887129, 2014). "The MIF and cyclin D1 proteins appeared to be located in the cytoplasm of tumor cells." (PMID 25015194, 2014).
tumor (continued). "MIF, a cytokine overexpressed in tumor microenvironments plays a critical role in several inflammatory conditions, as well xas in oncogenic transformation and tumor progression." (PMID 23497377, 2013). "However, nowadays MIF has been recognized to act as a pro-inflammatory cytokine which is both involved in inflammatory and immune responses, as well as in tumor cell growth and invasiveness." (PMID 24098347, 2013). "Recent studies have indicated that MIF can induce the generation and homing of Th17 cells to the tumor microenvironments; however, the function and clinical relevance of Th17 cells in tumor microenvironments were conflicting in different cancers." (PMID 23497377, 2013). "Our results suggest that the expression levels of MIF and CXCR4 were altered in the same way in different cell populations in the tumor microenvironments of ESCC and that the CXCR4 protein was a receptor response to MIF signaling in both immune cells and tumor cells." (PMID 23497377, 2013). "However, the association between the expression levels of MIF and CXCR4 in diverse cell populations of the tumor microenvironment and the survival of cancer patients remains ambiguous." (PMID 23497377, 2013). "Since many of the mechanisms responsible for the multifactorial functions of MIF have still to be identified, we have provided important new information with regard to the role of MIF in regulating tumor cell proliferation and programmed cell death by caspase-3 and caspase-4 dependent pathways." (PMID 23522304, 2013). "Furthermore, an inverse connection between miR-451 and MIF expression in biopsies of gastric tumors was observed, which suggested a role of miR-451 as a tumor suppressor." (PMID 22312290, 2012). "MIF could therefore act in a dual fashion both as an autocrine factor as well as a tumor-derived factor which influences the immune micromilieu." (PMID 22973314, 2012). "Whether MIF-induced autophagy will enhance tumor survival under stress condition and whether MIF inhibition is an alternative therapeutic approach against cancer must be further studied in the future." (PMID 22629429, 2012). "MIF over-expression in tumor tissues was confirmed both by IHC and western blot." (PMID 22461895, 2012). "Moreover, several reports have suggested that MIF plays additional roles as a growth factor-like molecule in the events of tumor cell growth and wound healing." (PMID 23050964, 2012). "Thus, based on its localization and functional features, MIF would be well in a position to execute important control of the tumor microenvironment." (PMID 22973314, 2012). "We speculate that the increased level of MIF protein observed at 42 dpi may indicate hypoxic adaptation within the tumour microenvironment." (PMID 23116199, 2012). "Recent studies have shown that MIF plays an important role in the tumor formation." (PMID 21438767, 2011). "In summary, we demonstrate that increased NPRA expression is strongly associated with progression of human PCa and that NPRA deficiency prevents growth of transplanted PCa cells and inhibits tumor burden in TRAMP mice in part by downregulating MIF in PCa cells." (PMID 21586128, 2011). "Finally, we studied, in vivo, the requirement of the MIF-RANTES axis for T lymphocyte migration to the tumor site." (PMID 21647415, 2011). "The results show that increased NPRA expression is strongly associated with progression of human PCa and that NPRA deficiency prevents growth of transplanted PCa cells and inhibits tumor burden in part by downregulating macrophage migration inhibitory factor (MIF) in PCa cells." (PMID 21586128, 2011). "Therefore, MIF functions as a novel growth factor that stimulates the uncontrolled growth and invasion of tumor cells." (PMID 24281172, 2010).
tumor (continued). "We speculate that intracellular MIF in the breast cells has a protective function, whereas extracellular MIF, be it TAM-derived or produced by carcinoma cells upon stroma/tumour interactions, is pathogenic." (PMID 19602265, 2009). "MIF is expressed in numerous cell types including tumour cells." (PMID 19602265, 2009). "Notably, treatment with 150 ng/ml rMIF not only stimulated endogenous MIF secretion constituting an autocrine loop, but led to a remarkable upregulation of MIF secretion in both non-invasive and invasive tumour cells." (PMID 19602265, 2009). "However, enhanced CD74-dependent tumour cell proliferation by autocrine MIF was also measured in MDA-MB-468 cells." (PMID 19602265, 2009). "MIF expression in tumor cell lines is regulated by growth factors and cell stress." (PMID 20038293, 2009). "The anti-tumour effect of cytosolic breast epithelial MIF might be mediated through JAB1/CSN5 which promotes p27 degradation and is counter-regulated by MIF or could reflect cell homeostatic activities of MIF." (PMID 19602265, 2009). "Evidence suggests that MIF may also indirectly support tumour growth via promotion of angiogenic responses." (PMID 19703290, 2009). "Our own evidence from chemical one-stage skin carcinogenesis experiments revealed that deletion of the MIF gene may lead to increased rates of tumor formation in mice." (PMID 17640378, 2007). "The absence of MIF did not impair tumor development but was associated with the absence of tumor invasion into muscle." (PMID 17650334, 2007). "These authors suggested that this finding may be the consequence of a reduced MIF synthesis or of an enhanced and altered secretion by tumor cells into the surrounding stroma." (PMID 16000172, 2005). "Besides, in the communication analysis between T cell subpopulations and MC subpopulations, we observed that MIF and CD99, key signaling molecules closely associated with tumor immune evasion, are involved in the active communication between T cell and MC subpopulations." (PMID 40932351, 2026). "Importantly, this mechanism supports our hypothesis: MIF abundantly secreted by tumor cells may disrupt the CXCR4-CXCL12 axis, interfering with germinal center reactions and thereby contributing to immune evasion." (PMID 41355948, 2026). "We identified RCC-specific features including enhanced T cell exhaustion, pro-angiogenic and immunosuppressive MC polarization, and a malignant CASC15+KLK6+ epithelial subpopulation that may drive tumor progression through MIF and CD99-mediated intercellular communication." (PMID 40932351, 2026). "Thus, the composition and activation state of infiltrating immune cells within the tumor microenvironment would influence whether the response to MIF is pro- or anti-tumorigenic." (PMID 41159021, 2025). "However, anti-MIF antibodies still face challenges related to tumor penetration and immunogenicity." (PMID 41159021, 2025). "According to a study, it was revealed that MIF overexpression in OSCC tissues is linked to perineural and deeper tumor invasion as well as lymph node invasion, resulting in a higher pathological stage and low overall survival rate and so it may be a potential marker for poor prognosis." (PMID 41159021, 2025). "Moreover, MIF inhibits the anti-tumor activity of NK cells, reinforcing its role in immune evasion." (PMID 41159021, 2025). "Additionally, specific inhibitors such as 4-iodo-6-phenylpyrimidine have been employed to disrupt MIF signaling, markedly enhancing tumor cell sensitivity to chemotherapy, suppressing primary tumor growth and angiogenesis, and significantly reducing the incidence of distant metastasis." (PMID 41127012, 2025). "Also, tumor-derived MIF enhances the expansion and migration of Th17 cells through CXCR4 signaling." (PMID 41159021, 2025).
tumor (continued). "In the MIF signalling pathway network, endothelial cells, myeloid cells, T cells and NK cells interact extensively, with endothelial cells notably interacting with tumour cells, T cells and macrophages, highlighting their critical role in the MIF signalling pathway." (PMID 40293350, 2025). "However, whether vessel formation is promoted via MIF-regulating pathways in tumor cells themselves (e.g. VEGF expression and secretion) or via VEGF-expressing macrophages, or a combination of both, remains elusive." (PMID 40835826, 2025). "Consequently, tumor-directed MIF inhibitors may provide additional therapeutic opportunities with improved potency and clinical relevance." (PMID 40835826, 2025). "Single-cell transcriptome analysis revealed CD36+ HCC-associated fibroblasts secreted MIF through increased intratumor lipid oxidation; the authors hypothesized that this induced a pro-tumor environment via lipid oxidation, which subsequently activates p38 kinase and drives MIF overexpression." (PMID 38732068, 2024). "Therefore, inhibiting MIF-CD74 signaling on macrophages via anti-MIF antibodies or MIF inhibitors could restore the antitumor immune response in tumor microenvironments." (PMID 38685050, 2024). "Interestingly, the primary source of MIF in tumors is the epithelial cells themselves, with a little secretory supply from stromal and inflammation-related cells, as well as other components of the tumor microenvironment." (PMID 38916819, 2024). "Additionally, MIF drives a stem cell-like phenotype, resulting in tumor dedifferentiation." (PMID 38732068, 2024). "The activation of the MIF - (CD74+CXCR4) axis indicates that IGF2BP1-overexpressing tumor cells may facilitate immune evasion through this pathway, consequently undermining anti-tumor immune responses and adversely impacting patient prognosis in immunotherapy contexts." (PMID 39512352, 2024). "Interestingly, both MIF and CD74 have been associated with tumor progression and metastasis." (PMID 39576827, 2024). "Single-cell analysis and cell communication indicated that PPP1R16A is predominantly distributed in liver malignant parenchymal cells and may reshape the tumor microenvironment by enhancing macrophage migration inhibitory factor (MIF)/CD74 + CXCR4 signaling pathways." (PMID 39010084, 2024). "Likewise, TNBC cells implanted into MIF-KO mice had reduced tumor growth." (PMID 38732068, 2024). "Furthermore, radiation improved tumor hypoxia to decrease HIF-1α dependent MIF secretion by NSCLC." (PMID 38685050, 2024). "We documented up-regulation in the expression of IFN-γ, IL12p70, IL-18, IL-20, MIF, TNF-α, TSLP, BLC, Eotaxin-1, Eotaxin-2, IP-10, MIP-1a, MIP-3a, FGF-2, MMP-1, TNFRII and TWEAK, which are implicated in the modulation of inflammation, apoptosis, tumor growth, invasion, and angiogenesis." (PMID 38954024, 2024). "IFN-γ signaling is particularly important in tumor infiltration and functions by polarizing tumor-associated macrophages (TAMs) from an M2-immunosuppressive type to an M1-pro-inflammatory type; however, it also reduces the presence of CD4 and CD8 T cells in the TME via MIF/CD74 signaling." (PMID 38732068, 2024). "This study revealed that serum MIF levels may be regarded as a promising serum tumor marker for BC." (PMID 38916819, 2024). "The MIF/CXCR4 axis could contribute to drug resistance in tumor invasion and metastasis." (PMID 39464891, 2024). "Thus, we analyzed the secretory factors in cultures of astrocytes and tumor cells and cocultures of these cells and found increased abundances of various soluble factors, such as MIF, CCL2, IL-6, and IL-8, primarily in astrocyte cultures compared to cultures of the other cell types." (PMID 38825648, 2024).